CCR6 (C-C motif chemokine receptor 6)
Diseases named in the same sentence as CCR6 in open-access papers (continued):
Sharing a sentence is not in itself a finding about the gene and the disease.
psoriasis (continued). "In addition, CLA+ CD4+ TCM cells expressing CCR6+ or CCR4+ CXCR3+ negatively correlated with the severity of psoriasis." (PMID 31963581, 2020). "NLP keratinocytes produce increased amounts of CCL20 upon stimulation with Candida albicans or mannan suggesting the role of KC, weakly stimulated by resident fungi, in accumulation of IL-17 and IL-22 producing CCR6-positive resident T cells in NLP skin of psoriasis patients." (PMID 32276410, 2020). "This suggests that the treatment may target CCR6+ γδ T17 cells expansion in the dLNs in mice with IMQ-induced psoriasis-like dermatitis." (PMID 31705000, 2019). "Thus, CCR6+ γδ T17 cells are thought to play a pivotal role in the development of psoriasis-like lesions." (PMID 31705000, 2019). "Moreover, they contribute to other autoimmune diseases such as psoriasis in which epidermal CCR6+ Vδ2+ cells express high levels of IL-17 and IL-22." (PMID 28076364, 2017). "In addition, we have shown previously that CCR6 is required for the psoriasis-like skin changes after injection of IL-23 (refs 17, 24, 31)." (PMID 27982014, 2016). "Recent study determines that CCR6+ Th17 cells have a critical role in psoriasis pathogenesis." (PMID 26901187, 2016). "Subcutaneous injections of IL-23 in mice induced psoriasis-like changes of erythema and induration as well as histological features such as acanthosis and parakeratosis, and this IL-23-induced psoriasis-like inflammation requires CCR-6." (PMID 23819059, 2013). "A critical role for CCR6 in the pathogenesis of psoriasis has been recently demonstrated." (PMID 21311769, 2011). "CCR6 has been reported to be crucial in the pathogenesis of psoriasis." (PMID 21311769, 2011). "The critical role of CCR6 in psoriasiform inflammation was well documented by the observation of expression of CCR6 and CCL20 in psoriatic lesions and by the finding that both IL-17A- and IL-22-producing cells isolated from lesional skin of patients with psoriasis displayed CCR6." (PMID 21311769, 2011). "An increase in the number of epidermal IL-17 and IL-22—producing skin-resident T CCR6 + cells—may be a genetically predisposed reaction to microbial stimulation in never-lesional skin in patients with psoriasis." (PMID 31963581, 2020). "Although CCR6 has been suggested to influence γδT17 cell migration during skin inflammation, activated γδT17 cells either emigrating from inflamed dermis during psoriasis or migrating into inflamed epidermis during a transgenic model of oncogenesis have lost CCR6 expression." (PMID 29731754, 2018). "It has been suggested that CCR6/CCL20 could be a potential therapeutic target for psoriasis." (PMID 24223818, 2013). "Therefore, the CCR6/CCL20 axis may be a promising target for treating psoriasis." (PMID 37092451, 2023). "CCR6+ T cells and CCL20 are abundant in the psoriatic skin of human psoriasis and experimental psoriasiform dermatitis." (PMID 37092451, 2023). "The nanoformulations of CUR were majorly able to decrease psoriasis inflammatory symptoms, PASI, TNF-α, IL-17, IL-22 and IL-1β levels, C-C chemokine receptor type 6 (CCR6) expression, the proliferation of psoriatic cells and occurrence of psoriatic lesions." (PMID 36678859, 2023). "The coordination between CCR6 and its ligand CC motif chemokine ligand 20 (CCL20) is deeply involved in the pathogenesis of various diseases, such as cancer, psoriasis, and autoimmune diseases." (PMID 37218898, 2023). "Thus, the CCL20/CCR6 axis could be a novel promising target for treating psoriasis." (PMID 37049538, 2023). "Another small molecule antagonist against CCR6 discovered by Chemocentryx is CCX2553, which has been shown to ameliorate inflammation in murine models of psoriasis." (PMID 37092451, 2023). "The chemokine receptor CCR6 is a GPCR that plays an important role in immunity and is involved in numerous diseases such as inflammatory bowel disease, psoriasis, multiple sclerosis and rheumatoid arthritis." (PMID 35203631, 2022).
psoriasis (continued). "IL-17 therapeutic blockade decreased CD3+CD4+CCR6+, CD3+CD4+CXCR3+, CD3+CD4+CCR6-CXCR3+(Th1), CD3+CD4+CCR6+CCR4+(Th17), CD3+CD4+CCR6+CCR4+CXCR3+(CXCR3+-Th17), and CD3+CD4+CCR6+CCR4-CXCR3+(Th17.1) cell populations in responding psoriasis patients." (PMID 35925616, 2022). "Increased CD3+CD4+CXCR3+, CD3+CD4+CCR6+CCR4+CXCR3+(CXCR3+-Th17), and CD3+CD4+CCR6+CCR4-CXCR3+(Th17.1) cell populations were observed in patients with psoriasis in comparison to healthy individuals (n = 10)." (PMID 35925616, 2022). "Using multiparameter flow cytometry we examined T-cell subpopulations characterized by CCR6, CCR4, and CXCR3 chemokine receptor surface expression at baseline and after initiation of biologic therapy in PBMCs collected from 30 psoriasis patients." (PMID 35925616, 2022). "In psoriasis, epidermal CD8+ TRM cells express CLA, CCR6, CD103 and IL-23R antigen and produce IL-17A during ex vivo stimulation." (PMID 31963581, 2020). "In a murine psoriasis model generated by intradermal IL-23 injection, treatment with an anti–CCL20 antibody significantly reduced the recruitment of CCR6+ cells and attenuated IL-23–induced psoriasiform dermatitis." (PMID 31936670, 2020). "Herein, we have shown increased expression of transcripts for TNF-α, of which the involvement in psoriasis is well-established, as well as CCL20 and hBD2, which are known to activate Th17 chemotaxis through CCR6." (PMID 28708859, 2017). "In the current study, we demonstrated that psoriasis-like inflammation requires moDCs, which produce the critical cytokines, TNF and IL-1β, and depend on CCR6 for their optimal accumulation in the skin." (PMID 27982014, 2016). "In a separate study, CLA+ CCR6+ γδ TCR+ cells in human blood were examined, and were found to be substantially reduced in the blood of psoriasis patients." (PMID 25649119, 2015). "Another theory is that obesity does not increase IL-17– and CCR6-expressing epidermal γδ T cells during psoriasis because of the experimental timeline we used." (PMID 40073267, 2025). "Metacluster 4 (CCR6- DP cells) was decreased and metaclusters 1 (Th17), and 11 (DN cells) were increased in psoriasis patients without arthralgia compared to HC." (PMID 35045868, 2022). "Collectively, these studies highlight that targeting CCR6 and/or CCR10 to inhibit the infiltration of ILCs into the skin could be a tremendously promising therapeutic alternative in psoriasis." (PMID 34831296, 2021). "Additionally, Vγ9Vδ2 T cells have been shown to produce psoriasis-relevant cytokines, such as IFN-γ, TNF-α, and IL-17A and chemokines such as IL-8, CCL3, CCL4, CCL5, and CCR6." (PMID 33732249, 2021). "Taking the example of psoriasis, skin with clinically resolved psoriasis was demonstrated to contain increased IL-17 mRNA expressing CD103+CD8+ TRM, and an enrichment of IL-23 responsive CD103+CCR6+IL23R+CD8+ T cells." (PMID 33669367, 2021). "Thus, the suppression of CCR6+ γδ T17 cells by Cal, BDP, or Cal/BDP corresponded to the effects of these agents on psoriasis-like dermatitis." (PMID 31705000, 2019). "For instance, S100A8 and S100A9 form a complex called calprotectin that aggravates psoriasis by regulating expression of the C3 complement factor, while hBD-2 promotes chemotaxis of various leukocytes in a C-C chemokine receptor (CCR) 2- and CCR6-dependent manner." (PMID 30918469, 2019). "In addition, downregulation of CCL20 and CCR6 by rERDR1 administration was also detected, implying that ERDR1 alleviates the psoriasis-like skin inflammation through the regulation of Th17 cell distribution in lesional skin." (PMID 26901187, 2016). "In addition, the HA-ES group loaded with CUR showed relief of inflammatory symptoms according to the clinical psoriasis area and severity index (PASI), lower levels of TNF-α, IL-17A, IL-17F, IL-22, and IL-1β mRNA, and lower CCR6 protein expression compared to ES and PGS groups." (PMID 36678859, 2023).
psoriasis (continued). "Similar to the CCL19/CCL21/CCR7 axis, the CCL20/CCR6 axis serves an essential role in the recruitment of inflammatory cells in the immune response and may contribute to a variety of autoimmune diseases, such as MS, IBD, psoriasis, and RA." (PMID 35702353, 2022). "In several animal models of psoriasis, the use of anti‐TNF‐α antibody infliximab, anti‐CCR6 antibody, and the anti‐CCL20 antibody, respectively, significantly reduced regional infiltration of CCR6+CD4+ T cells and attenuated the inflammatory response in affected skin lesions." (PMID 35702353, 2022). "Here we show that psoriasis-like pathology induced either by direct injection of IL-23 or by the application of IMQ requires inflammatory moDCs, and that, at least in the IL-23 injection model, CCR6 is important for the accumulation of these cells through its role in monocyte recruitment." (PMID 27982014, 2016). "Based on increasing evidence for the importance of the CCR6+ Th17 cell population in psoriasis, we suggest that a decreased distribution of CCR6+ Th17 cells in psoriatic lesional skin via the regulation of CCL20 may be a critical mechanism for ERDR1-regulated psoriasis." (PMID 26901187, 2016). "Obesity increases the number of CCR6- and IL-17–expressing epidermal γδ T cells during the early stages of wound repair but not during IMQ-induced psoriasis." (PMID 40073267, 2025). "Upregulation of CCR6 by epidermal γδ T cells in psoriasis occurs in both NCD- and HFD-fed mice to a similar degree, suggesting that obesity does not exacerbate CCR6 expression at this time point of IMQ-induced psoriasis onset." (PMID 40073267, 2025). "In contrast, the lack of CCR6 and CCR10 expression suggests a less skin inflammatory profile of CU than AD and psoriasis, where both receptors are well-described for their role." (PMID 37371632, 2023). "In murine psoriasis, γδ T cells migrate into lesions via CCR2 and CCR6; moreover, they can travel to distal noninflamed skin and LNs to provide memory activation under restimulation." (PMID 35296088, 2022). "Psoriasis patients without arthralgia showed lower numbers of CCR6-CXCR3+CCR4+ cells and higher numbers of CCR6+ DN cells." (PMID 35045868, 2022). "Deletion of CCR6 or the dominant-negative form of CCL20 ameliorates skin symptoms in psoriasis model mice, thus suggesting the indispensable role of the CCL20/CCR6 axis in the pathogenesis of psoriasis." (PMID 34361983, 2021). "Importantly, both the Lin− CD123low and CD127+ populations were increased in the skin of psoriasis patients; however, it is possible that the CD127+ ILC may migrate by a mechanism independent of CXCR4/SDF-1 but CCR6-dependent because high levels of CCR6 were identified in the CD127+ ILC population." (PMID 28303135, 2017).
autoimmune disease (53 papers, 2008 to 2026). A disorder resulting from loss of function or tissue destruction of an organ or multiple organs, arising from humoral or cellular immune responses of the individual to their own tissue constituents. "Earlier it has been identified that ICOS, CTLA4 and CCR6 polymorphism is related to autoimmune disease risk in patients with Sarcoidosis28–30." (PMID 35075176, 2022). "Both Th17 and regulatory (Treg) cells express CCR6, which has been linked to the susceptibility to autoimmune diseases." (PMID 34829761, 2021). "This is the case of CXCR3 and CCR6, which are associated with the recruitment of pathological Th1; Th17 and Th17.1 in various inflammatory and autoimmune disorders." (PMID 28873441, 2017). "Various studies using CCR6-deficient mice or CCR6 inhibitors indicate the potential of this receptor as a therapeutic target in autoimmune disease." (PMID 28873441, 2017). "The pathogenesis of various autoimmune diseases and inflammatory diseases has been linked to the involvement of Th17 cells, most of them reporting CCR6 as a key factor for involvement of Th17 cells." (PMID 25928629, 2015). "The selection of SNPs around CCR6 were based on earlier autoimmune disease associations reported by others, including a number of autoimmune diseases, including RA, Crohn’s disease and vitiligo." (PMID 23935994, 2013). "A common issue linking CCR6 expressing Th cells and Th17 cells is their association with autoimmune diseases." (PMID 18698357, 2008). "Activation of the chemokine receptor CCR6 orchestrates the trafficking of IL-17-producing pathogenic immune cells to the sites of inflammation, thus contributing to the development of numerous inflammatory and autoimmune diseases." (PMID 41613106, 2026). "Data from these results indicate that the CCL20/CCR6 axis is implicated in the pathogenesis of autoimmune diseases and that antibodies or antagonists to CCR6 or CCL20 hold promise as an intriguing treatment tactic to ameliorate neuroinflammation and autoimmunity." (PMID 35702353, 2022). "A number of autoimmune diseases may share similar gene susceptibility and previous studies have reported significant associations between genetic polymorphisms of CCR6 and certain autoimmune diseases such as RA, Crohn’s disease, SSc and vitiligo." (PMID 25928629, 2015). "The recruitment of Th17 cells via the CCL20/CCR6 axis was associated with development of autoimmune diseases, thereby rendering the CCL20/CCR6 axis a prospective novel target for the management of autoimmune conditions, inclusive of CP/CPPS." (PMID 38801403, 2024). "The hyper-activation of the CCL20–CCR6 axis leads to autoimmune disease, making CCR6 a promising therapeutic target to prevent this type of disease." (PMID 38551001, 2024). "The dysregulation of CCL20 or CCR6 can give rise to a large number of diseases including many inflammatory and autoimmune diseases." (PMID 38472446, 2024). "CCR6 is a potential target in treating various diseases, such as cancer, inflammatory and autoimmune disorders." (PMID 37092451, 2023). "Since rheumatoid arthritis is considered a TH17/TH22-related autoimmune disorder, this report suggests that CCR6 or CCR10 should be considered as potential drug targets." (PMID 37760825, 2023). "In general, the presence of the CCR6 molecule characterizes the T helper population, referred to as Th17/22 in our article, which is involved in the inflammatory response in autoimmune diseases and exhibits increased pathogenicity." (PMID 36676614, 2023). "Th17 cells are associated with a wide array of inflammatory conditions, including autoimmune diseases, with a strong correlation between CCR6 expression and disease severity." (PMID 35572511, 2022). "Ccl20 binds to its unique receptor, Ccr6, to recruit Th17 cells and B cell subsets that have important roles in progression of autoimmune disease." (PMID 35472067, 2022).
autoimmune disease (continued). "An LD block on chromosome 6 (6q27) that contains the genes CCR6 and FGFR10P was observed to be associated with increased risks for several autoimmune diseases, such as RA, Crohn’s disease, and vitiligo." (PMID 35213968, 2022). "Ccr6 regulates the migration of inflammatory and regulatory T cells (Th17 and Treg), which play opposite roles in autoimmune diseases." (PMID 32922257, 2020). "Using rheumatoid arthritis (RA) as a model of autoimmune disease, we here demonstrate that pro-inflammatory memory CCR6+ Th cells can switch into anti-inflammatory cells with regulatory capacity using the active vitamin D metabolite 1,25(OH)2D3." (PMID 31379807, 2019). "For the conversion from a pro-inflammatory IL-17A-producing memory CCR6+ Th cell to a regulating cell to be functional in suppressing autoimmune diseases, the cells should migrate toward the site of inflammation." (PMID 31379807, 2019). "Inhibition of CCR6 is proposed to attenuate disease symptoms and promote recuperation of multiple inflammatory and autoimmune disorders." (PMID 30453514, 2018). "Data available from preclinical studies of research again highlights CCX9664 as a novel CCR6 antagonist that is capable of reducing disease severity in rheumatoid arthritis, a common autoimmune disease which affects the joints in the skeletal system." (PMID 30453514, 2018). "The role of CCR6 is constitutively expressed as a series of much debilitating severe inflammatory and autoimmune diseases, Human Immunodeficiency Virus (HIV) and cancer metastasis." (PMID 30004409, 2018). "CCR6 expression by Th17 cells allows their migration across the endothelial barrier in several autoimmune diseases such as multiple sclerosis or RA." (PMID 29887869, 2018). "This study was designed to determine the association of CCR6 and FGFR10P (tag)SNPs with Vogt-Koyanagi-Harada (VKH) syndrome, an autoimmune disease directed against melanocytes, in two independent Chinese Han populations." (PMID 23935994, 2013). "An LD block on chromosome 6 in the region of the genes encoding for CCR6 and FGFR1OP (6q27) has been shown to be associated with an increased risk for a variety of autoimmune diseases, such as rheumatoid arthritis (RA), Crohn’s disease and vitiligo." (PMID 23935994, 2013). "CCR6-expressing Th cells have been intensively studied in autoimmune diseases and chronic inflammations." (PMID 23028548, 2012). "While CCR6 has been demonstrated to recruit Treg cells to the inflamed tissues in several autoimmune diseases, in leishmaniasis the receptor seems to be important for Treg cell accumulation in the lymph nodes where they regulate the inflammatory response." (PMID 23028548, 2012). "In humans, CCR6 and/or MIP-3α/CCL20 have been implicated in the pathogenesis of rheumatoid arthritis and inflammatory bowel disease, autoimmune disorders in which Th17 cells are thought to play a crucial role." (PMID 23283206, 2009). "CCR6, IRF5, and CD40 are all well-known autoimmune disease genes associated with RA or AS34–37." (PMID 38360850, 2024). "In addition, another novel gene, IL2RA interacts with the well-known autoimmune disease genes CCR6, IRF5, and CD40, which are the hub genes in the network." (PMID 38360850, 2024). "In addition, ccl20 is a chemokine whose sole ligand is c-c motif chemokine receptor 6 (ccr6), and it also plays an important role in autoimmune diseases." (PMID 37238005, 2023). "However, inhibiting CCR6 will also affect the recruitment of other anti-tumor cells or lead to the onset of autoimmune diseases in vivo because Tregs are also recruited to other tissues by CCR6 to play an immunosuppressive role." (PMID 37936703, 2023). "Pro-inflammatory Th17 cell populations, which are distinguished by the expression of CCR6 and include Th17, Th1/Th17, and Th17.1 cells, are elevated and more active in various autoimmune diseases including RA, systemic lupus erythematosus, and inflammatory bowel diseases." (PMID 31379807, 2019).